PHTF1 (putative homeodomain transcription factor 1)
Synonyms: PHTF
Tractability: Antibody: UniProt predicts a signal peptide or a membrane-spanning region. PROTAC: ubiquitination databases record sites on it.
Gene: Protein-coding gene on chromosome 1 (113,696,052 to 113,759,908, reverse strand). Ensembl gene ENSG00000116793.
Subcellular location: Endoplasmic reticulum membrane; Golgi apparatus, cis-Golgi network membrane
Subcellular location (Human Protein Atlas): Nuclear bodies; Nucleoli
Gene Ontology:
Cellular component: endoplasmic reticulum membrane; endoplasmic reticulum; Golgi apparatus
Genetic constraint (gnomAD): Loss-of-function variants: 35 observed, 46.73 expected, observed/expected ratio (o/e) 0.75, 90% interval 0.57 to 0.99. The upper end of that interval is the gene's LOEUF score, 0.99, which puts it in group 4 of 6, group 1 being the genes least tolerant of losing a copy. Missense variants: 445 observed, 510.47 expected, observed/expected ratio (o/e) 0.87, 90% interval 0.81 to 0.94. Synonymous variants: 156 observed, 174.21 expected, observed/expected ratio (o/e) 0.9, 90% interval 0.79 to 1.02.
Homologues: Orthologues: chimpanzee PHTF1 (99% identical), dog PHTF1 (96% identical), guinea pig PHTF1 (95% identical), macaque PHTF1 (95% identical), rat Phtf1 (94% identical), pig PHTF1 (94% identical), mouse Phtf1 (94% identical), rabbit PHTF1 (90% identical), tropical clawed frog rsbn1 (60% identical), zebrafish phtf1 (50% identical), Drosophila melanogaster phtf (35% identical). Paralogues in human: PHTF2 (54% identical).
Diseases named in the same sentence as PHTF1 in open-access papers:
PHTF1 is named in the same sentence as 20 diseases in open-access papers, as found by Europe PMC text mining. Sharing a sentence is not in itself a finding about the gene and the disease. The quoted sentences say what the papers report.
breast carcinoma (2 papers, 2015 to 2018). "For instance, PHTF1, MUC5AC, ZNF192, PCSK6, and HDGFRP3 are shown to be involved in breast cancer, and some common genes such as DCT, ZP2, and CEACAM7 might be involved in breast cancer." (PMID 29589558, 2018). "For instance, PHTF1, ZNF192, and MUC5AC are already shown to be involved in breast cancer." (PMID 29589558, 2018). "At the DCLRE1B/PHTF1 locus, we were unable to definitively rule out one of those genes when we examined the overlap with the posterior probability of breast cancer." (PMID 26472073, 2015).
acute lymphoblastic leukemia (1 paper, 2015). Leukemia with an acute onset, characterized by the presence of lymphoblasts in the bone marrow and the peripheral blood. "Previous study showed that downregulated BCL11B expression in T cell acute lymphoblastic leukemia (T-ALL) cell line Molt-4 inhibited cell proliferation and induce apoptosis, which may be related to PHTF1 gene overexpression." (PMID 26448723, 2015).
leukemia (1 paper, 2015). A malignant (clonal) hematologic disorder, involving hematopoietic stem cells and characterized by the presence of primitive or atypical myeloid or lymphoid cells in the bone marrow and the blood. "However, studies on the PHTF1 gene in leukemia have not been reported." (PMID 26448723, 2015).
rheumatic diseases (1 paper, 2024). "We would like to highlight that the variant rs6679677, which was significantly associated with T1DM, is situated between PHTF1 (Putative Homeodomain Transcription Factor 1) and RSBN1, which are implicated in systemic seropositive rheumatic diseases." (PMID 38256693, 2024).
tumor (3 papers, 2015 to 2022). "Therefore, we considered that PHTF1 has tumor-suppressive activity and triggers the PHTF1-FEM1b-Apaf-1 apoptosis pathway using in vitro assays." (PMID 26448723, 2015). "PHTF1 may be a tumor-suppressor like gene and a therapeutic target for triggering the PHTF1-FEM1b-Apaf-1 apoptosis pathway." (PMID 26448723, 2015). "Therefore, we hypothesized that the BCL11B gene and the PHTF1-FEM1b-Apaf-1 pathway may work together in tumor cell apoptosis." (PMID 26448723, 2015). "In addition, other genes have been involved in cancer processes, such as interference with innate immune system (SH2D3C), apoptosis (BLCAP), crossing-over regulation during meiosis (RNF212), and tumor suppression (ZDHHC14, MIR138-2, and PHTF1)." (PMID 36535927, 2022).
cancer (2 papers, 2021 to 2022). A tumor composed of atypical neoplastic, often pleomorphic cells that invade other tissues. "The H61Y SNP (rs11552449) is associated with cancer risk due to its correlation with alternative splicing of the SNM1B and PHTF1 transcripts, each also associated with increased cancer risk and (for the SNM1B transcript) to cellular sensitivity towards mitomycin C and IR." (PMID 34387694, 2021).
hematologic malignancies (1 paper, 2015). "Real-time PCR was used to determine the gene expression level of PHTF1 in hematologic malignancies." (PMID 26448723, 2015).
hematological cancers (1 paper, 2023). "Although its essential paralog PHTF1 has been overexpressed in T‐ ALL cell lines to regulate cell proliferation and apoptosis, the association of PHTF2 with other hematological cancers has not been reported." (PMID 38069522, 2023).
PHTF1 also shares sentences with these, for which no sentence is quoted: Type 1 diabetes (2 papers); acute myeloid leukemia (1); autoimmune thyroid disease (1); depression (1); diabetes (1); Graves disease (1); Hashimoto thyroiditis (1); hypothyroidism (1); Obesity (1); papillary thyroid cancer (1); rheumatoid arthritis (1); schizophrenia (1).